HGF (hepatocyte growth factor)
Diseases named in the same sentence as HGF in open-access papers (continued):
Sharing a sentence is not in itself a finding about the gene and the disease.
myeloma (continued). "Abnormal activation of the HGF/Met axis is established in solid tumours and in chronic haematological malignancies, including myeloma, acute myeloid leukaemia, chronic myelogenous leukaemia (CML), and myeloproliferative neoplasms (MPNs)." (PMID 25119536, 2014). "HGF secretion in co-cultures of human myeloma cell lines and bone marrow stromal cells was measured by ELISA." (PMID 24716444, 2014). "Gene array analysis along with numerous other studies by us and others, identified the HGF/MET axis as a therapeutic target in myeloma." (PMID 24326130, 2013). "HGF/MET signaling is increasingly recognized as an important contributor to the pathogenesis of myeloma." (PMID 24326130, 2013). "In the present study, we compared mRNA levels of MET and HGF in normal and primary myeloma plasma cells." (PMID 24326130, 2013). "A 48-hr amuvatinib treatment in high HGF-expressing myeloma cell line, U266, resulted in growth inhibition." (PMID 24326130, 2013). "Some MM cell lines and primary myeloma cells also secrete HGF, suggesting the occurrence of paracrine/autocrine interactions between microenvironmental cell types and myeloma cells in vivo." (PMID 22567028, 2012). "Among all potential angiogenic cytokines, hepatocyte growth factor has been acknowledged as the pivotal factor involved in multiple myeloma angiogenesis." (PMID 22629140, 2012). "Our paper in addition compares serum levels of HGF in the most prominent phases of multiple myeloma, that is, at the time of diagnosis, in remission and in relapse/progression of the disease in comparison with MGUS." (PMID 22629140, 2012). "Our interest in HGF as a candidate stimulus driving IDO1 expression in MM stems from studies underpinning the role of HGF in myeloma pathogenesis and from our previous report on the ability of HGF to induce IDO1 in human DC." (PMID 23232072, 2012). "Various angiogenic cytokines, such as vascular endothelial growth factor (VEGF) and hepatocyte growth factor (HGF) increase myeloma cell proliferation and accelerate bone resorption." (PMID 21941412, 2011). "The results indicate that besides from being a myeloma growth factor alone, HGF can also potentiate the effects of IL-6 in myeloma proliferation and migration." (PMID 19187270, 2009). "Compared to healthy controls, bone marrow plasma from multiple myeloma patients contained high levels of HGF." (PMID 19187270, 2009). "Myeloma cell lines and primary samples were tested for the combined effects of IL-6 and HGF in inducing DNA synthesis and migration." (PMID 19187270, 2009). "Though there are exceptions, when tested for ability to induce cell proliferation or prevent apoptosis in a large number of myeloma cell lines or primary myeloma cells, HGF generally have had limited effects (H. Hov and M. Børset, unpublished data)." (PMID 19187270, 2009). "Despite these findings, HGF generally appears to be a weak growth factor for myeloma cells in vitro." (PMID 19187270, 2009). "Because elevated HGF expression has been reported to characterize a subgroup of the hyperdiploid myeloma patients, we analyzed some of the most common genetic aberrations in our primary samples by FISH." (PMID 19187270, 2009). "Recently, HGF and c-Met have been found to be significantly dysregulated in gene expression profiling experiments on purified plasma cells from multiple myeloma patients." (PMID 19187270, 2009). "It has previously been shown by us and others HGF can act as a growth factor to myeloma cells in vitro although these effects have been moderate." (PMID 19187270, 2009). "The main results were that myeloma cells produce HGF, and that high serum levels of HGF at diagnosis correlated with poor prognosis for patients." (PMID 19187270, 2009). "Immunohistochemical staining for HGF on bone marrow biopsies revealed that plasma cells from almost all myeloma patients stained positive for HGF (K. W. Wader, unpublished data)." (PMID 19187270, 2009).
myeloma (continued). "Hepatocyte growth factor (HGF) is a constituent of the myeloma microenvironment and is elevated in sera from myeloma patients compared to healthy individuals." (PMID 19187270, 2009). "HGF is found in bone marrow plasma of both healthy subjects and myeloma patients, and bone marrow stromal cells constitutively produce HGF." (PMID 19187270, 2009). "HGF potentiated IL-6-induced growth in human myeloma cell lines and in purified primary myeloma cells." (PMID 19187270, 2009). "HGF was the only growth factor among 70 highly expressed genes in malignant plasma cells compared to normal bone marrow plasma cells, and HGF and IL-6 were also shown to characterize one of four clusters of hyperdiploid myeloma." (PMID 19187270, 2009). "The complex mechanisms regulating activation of HGF in multiple myeloma, including a potential role for the HGFA inhibitors HAI-1 and HAI-2, should be addressed in further studies." (PMID 18691255, 2008). "HGF has a number of myeloma-relevant activities; however, it has to be converted to its heterodimeric form to be biologically active." (PMID 18691255, 2008). "The median HGF concentrations in myeloma and control sera were 2.5 (range 0.7–8.0) and 1.6 ng/mL (range 0.5–4.0), respectively." (PMID 18691255, 2008). "HGF is produced by myeloma cells and by stromal cells in the bone marrow microenvironment, and thereby acts in an autocrine or paracrine manner through its receptor c-Met." (PMID 18691255, 2008). "We here show for the first time that the activated form of HGFA is present at high levels in serum and bone marrow of myeloma patients, thus providing a necessary prerequisite for the activation of HGF." (PMID 18691255, 2008). "Although this study has obvious limitations because of the relatively small number of study subjects, it clearly demonstrates the presence of a necessary prerequisite for activation of the HGF system in multiple myeloma." (PMID 18691255, 2008). "In multiple myeloma, Sdc1 mediates ligand binding and signalling through the hepatocyte growth factor (HGF) receptor tyrosine kinase c-met, resulting in increased cancer cell proliferation." (PMID 17244359, 2007). "In addition, the HGF/MET pathway is also considered an important therapeutic target in multiple myeloma." (PMID 40110197, 2025). "Our study suggests that HGF has an important role in multiple myeloma." (PMID 38690165, 2024). "MM cell lines and primary myeloma cells secrete HGFA which can then activate HGF." (PMID 37568580, 2023). "The demonstration that decorin inhibited HGF-induced viability and migration of myeloma cell lines in vitro suggests that deregulation of the physiological crosstalk among decorin, HGF, and c-MET could have a role in disease pathogenesis." (PMID 35582373, 2021). "The aim of this review is to summarize the key findings on the pathogenetic activity of HGF in multiple myeloma and further describe novel therapeutic approaches potentially helpful to overcome signals provided by the HGF/c-MET axis, putatively involved in drug resistance." (PMID 35582373, 2021). "Myeloma cells stimulate BMSCs to secrete HGF, VEGF, and IL8 to induce neovascularization." (PMID 33634031, 2020). "Another autocrine loop involved in myeloma survival is secretion of HGF." (PMID 33634031, 2020). "Indoleamine 2,3 dioxigenase-1 (IDO-1), an enzyme involved in tryptophan metabolism, is also overexpressed by myeloma cells through the action of HGF, which increases the generation of kynurenines that contribute to the immune suppressive microenvironment in the BM28." (PMID 32829378, 2020). "Indeed, the prognosis of patients with multiple myeloma (MM) is worse in the presence of high HGF levels in serum and a direct correlation between serum HGF levels and disease aggressiveness has been demonstrated." (PMID 30642077, 2019).
myeloma (continued). "However in some malignancies such as in Philadelphia chromosome negative and positive (Ph− or Ph+) myeloproliferative neoplasms (MPNs) or in multiple myeloma (MM) HGF derives from cells of the microenvironment but also from leukemic cells or their progenitors." (PMID 30642077, 2019). "Together, these findings supported the hypothesis that suppressing HGF/c-MET signaling could be a rational strategy against relapsed/refractory myeloma, and we therefore performed a phase II clinical trial testing this possibility." (PMID 28337527, 2017). "Moreover, the tumor microenvironment releases growth factors for myeloma cells including HGF, matrix metalloproteinases (MMPs), fibroblast growth factor-2, MCP-1 (monocyte chemotactic protein-1), and others." (PMID 27764795, 2016). "In addition, HGF existed in a complex form with soluble SDC1 in pleural effusions, suggesting an important role of soluble SDC1 as a carrier for HGF in the pathology of myeloma." (PMID 26293675, 2015). "We here show that in myeloma patients HGF is primarily produced by malignant plasma cells, and that HGF production by these cells might be supported by the bone marrow microenvironment." (PMID 24716444, 2014). "High HGF levels found in the blood and bone marrow of myeloma patients could either be the result of HGF overexpression in malignant PCs or due to a reactive process within the bone marrow which is a result of the presence of malignant PCs." (PMID 24716444, 2014). "Similarly, HGF levels were also reported to be high in myeloma, both in the blood of patients and in supernatants from malignant plasma cells." (PMID 25119536, 2014). "Investigating the role of myeloma cells in the production of HGF, we found a clear correlation not only between HGF mRNA levels in malignant PCs and bone marrow core biopsies of myeloma patients, but also between HGF mRNA levels and HGF serum concentrations of corresponding samples." (PMID 24716444, 2014). "The absence of mutations that could explain the high HGF expressing phenotype of certain myeloma cell clones points to other mechanisms that induce excessive HGF production." (PMID 24716444, 2014). "The lack of correlation between HGF mRNA in bone marrow core biopsies and the percentage of MM cells in corresponding samples suggests that HGF is either produced by non-myeloma cells or, if by malignant PCs, that malignant PCs show huge variation between patients in their capacity to produce HGF." (PMID 24716444, 2014). "In myeloma, HGF-c-MET signaling was reported to induce myeloma cell proliferation and survival." (PMID 24716444, 2014). "HGF mRNA levels in biopsies and in myeloma cells correlated." (PMID 24716444, 2014). "In this study, we investigated the origin of elevated HGF levels found in myeloma patients." (PMID 24716444, 2014). "We therefore investigated if the bone marrow microenvironment could induce excessive HGF production in certain myeloma cells." (PMID 24716444, 2014). "Since the origin of excess HGF in myeloma patients is still unknown, we hypothesized that the bulk of HGF found in myeloma patients is produced by malignant PCs, and not by the bone marrow microenvironment." (PMID 24716444, 2014). "Cytogenetic analysis showed myeloma cell clones with HGF copy numbers between 1 and 3 copies." (PMID 24716444, 2014). "The increase in HGF production in co-cultures of myeloma cells with stromal cells could also be seen with different types of stromal cells." (PMID 24716444, 2014). "In the late 90s the Nordic Myeloma Study group concluded that high serum HGF levels could be used to identify patients with a poor response to treatment, suggesting that the HGF level reflects tumour burden and could be a marker of disease activity." (PMID 25119536, 2014). "Based on this background, we hypothesized that targeting the HGF/MET signaling pathway is a rational approach to myeloma therapy and that myeloma cells would be sensitive to amuvatinib." (PMID 24326130, 2013).
myeloma (continued). "Moreover, amuvatinib treatment resulted in cell death in U266 myeloma cell line dependent on MET/HGF signaling, as measured by annexin V/PI staining and PARP cleavage." (PMID 24326130, 2013). "Together, these findings provide a rationale for targeting the HGF/MET signaling axis in myeloma." (PMID 24326130, 2013). "Furthermore, HGF not only promotes growth, migration, and survival of myeloma cells, it also potentiates IL-6 effects." (PMID 24326130, 2013). "Besides its effects on the malignant myeloma cells, HGF is involved in the pathogenesis of myeloma-related bone disease." (PMID 24326130, 2013). "Targeting HGF directly may prove difficult, since therapeutic targeting of HGF would need to be effective at elevated levels to successfully compete and inhibit the high serum HGF concentrations in myeloma patients." (PMID 24326130, 2013). "While levels of plasma HGF have been associated with myeloma, levels of HGF and MET mRNA in patient plasma cells have not been well evaluated nor correlated with disease status." (PMID 24326130, 2013). "In myeloma, a B-cell plasma malignancy, MET is neither mutated nor over-expressed, however, HGF is increased in plasma or serum obtained from myeloma patients and this was associated with poor prognosis." (PMID 24326130, 2013). "Taken together, these clinical findings strongly support our hypothesis that targeting the HGF/MET signaling pathway is a rational approach to myeloma therapy." (PMID 24326130, 2013). "Therefore, NF-κB activation in BMSCs enhances positive loop with adherent multiple myeloma cells by secretion of growth factors such as IL-6, TNFα, and HGF." (PMID 24151609, 2013). "It is interesting to note that even samples with lower HGF mRNA levels in the plasma cells, typically had higher levels than the samples from healthy individuals; the 25th percentile for the myeloma patient HGF levels was > the 75th percentile for healthy individuals." (PMID 24326130, 2013). "Patients with multiple myeloma have significantly higher levels of HGF than healthy controls." (PMID 22629140, 2012). "Possible role of HGF as an auxiliary diagnostic and prognostic tool documented by significant differences between active disease and premalignant MGUS or remission phase myeloma is, however, attenuated by certain overlapping of marginal values in all the groups." (PMID 22629140, 2012). "The Nordic Myeloma Study Group has shown that HGF is elevated in 25% of patients at diagnosis." (PMID 22567028, 2012). "In the context of multiple myeloma, HGF was found to have an impact on bone disease, too." (PMID 22629140, 2012). "Although MM cells were shown not to express a significantly higher number of pro- or antiangiogenic genes compared with normal plasma cells, 97% of myeloma samples express at least one angiogenic factor among the 6 most frequently expressed factors, including HGF." (PMID 22567028, 2012). "HGF and its receptor c-met are expressed simultaneously in myeloma cells." (PMID 21941412, 2011). "Moreover, syndecan-1 binds HGF on the surface of myeloma cells bringing HGF in close proximity of its receptor c-Met." (PMID 19187270, 2009). "Some 10 yr ago, we found that hepatocyte growth factor (HGF) may play a role in multiple myeloma, a finding later confirmed by various techniques in different laboratories." (PMID 19187270, 2009). "Targeting HGF/c-Met may therefore attenuate growth promotion by other growth factors than HGF, and c-Met signaling may be a target for therapy also in multiple myeloma." (PMID 19187270, 2009). "Hepatocyte growth factor (HGF) is a potential key factor in multiple myeloma." (PMID 18691255, 2008). "In addition, it has been recently shown that, in osteoblast-like cells, HGF/c-MET signaling could also be mediated by extracellular vesicles (EV) released by myeloma cells." (PMID 35582373, 2021).
myeloma (continued). "In addition, HGF inhibits BMP-2-induced generation of osteoblasts in multiple myeloma, prompting the continued proliferation of MSCs and thus could promote chondroblast proliferation and cartilage formation in conjunction with BMP-4." (PMID 26098852, 2015). "Moreover, the c-MET inhibitors were found to block the response to HGF in a myeloma model." (PMID 26543328, 2015). "In conclusion, there were no obvious mutations in the HGF promoter of the myeloma cells investigated that could explain the variation in HGF mRNA expression." (PMID 24716444, 2014). "Moreover, plasma cells expressed HGF and Met, confirming an autocrine HGF/Met loop also in myeloma." (PMID 25119536, 2014). "Interestingly, myeloma cells catalyze HGF activation by secreting HGFA." (PMID 22567028, 2012). "Studies in myeloma models revealed dual roles for HPSE in HGF activity: high serum levels of HPSE, shed SDC-1, and HGF correlate with poor prognosis, reflecting functional cooperation." (PMID 41301515, 2025). "Myeloma cells secrete angiogenic factors such as VEGF, hepatocyte growth factor (HGF), fibroblast growth factor-2 (FGF-2), and insulin like growth factor-1 (IGF-1), thereby enhancing cell proliferation and survival." (PMID 41471085, 2025). "Exosomes derived from multiple myeloma contain VEGF, bFGF, MMP-9, hepatocyte growth factor (HGF), and serpin E1." (PMID 38200509, 2024). "Our earlier study showed that an antagonist against HGF, that is, NK4, also inhibited HGF/c‐MET signaling and anti‐angiogenic activity in a mouse MM xenograft model, indicating the growth dependency of myeloma cells on HGF/c‐MET." (PMID 36825580, 2023). "Increased HAT activity in Hpse-high myeloma cells resulted in upregulation of transcription of multiple genes (i.e., VEGF, HGF, MMP-9, RANKL) that drive an aggressive tumor phenotype." (PMID 36980232, 2023). "HGF is a pleiotropic cytokine involved in the progression of the monoclonal gammopathy of undetermined significance (MGUS) to MM, myeloma cell proliferation and survival." (PMID 37568580, 2023). "A vicious cycle is established, driven by the secretion by BMSCs of factors that promote the proliferation of myeloma cells (IL-6, IGF-1, transforming growth factor (TGF)-β, and hepatocyte growth factor (HGF)." (PMID 36212502, 2022). "Several cytokines in the BM microenvironment facilitate homing of myeloma cells, including stromal cell-derived factor (SDF)-1α and hepatocyte growth factor (HGF), both of which have been shown to mediate the activation of Src kinase." (PMID 36268559, 2022). "In myeloma cells, HGF binds to cell surface-bound SDC-1 with the resultant SDC-1/HGF complex stimulating cell migration via the c-Met receptor upon SDC-1 cleavage." (PMID 35118073, 2021). "Of the five human myeloma cell lines tested, only JJN3 showed a significantly high HGF gene expression, supporting previous findings." (PMID 29924867, 2018). "Previously it was demonstrated that 5T33MM murine myeloma cells and inflammatory cells in the mouse BM microenvironment secrete angiogenic factors such as VEGF and HGF." (PMID 29568363, 2018). "HGF and c-MET expression at the mRNA and protein levels has been found in most myeloma cell lines and primary samples." (PMID 28337527, 2017). "In myeloma patients, diverse angiogenic factors such as VEGF, endoglin, TNF-alpha, HGF, FGF, endostatin, thrombospondin-1 (TSP-1), and angiostatin factor are already well studied in peripheral blood and bone marrow." (PMID 28727816, 2017). "Activation of the c-MET receptor tyrosine kinase induced by its ligand, hepatocyte growth factor (HGF), plays a role in myeloma pathobiology." (PMID 28337527, 2017). "Aberrant activation of HGF and/or its receptor c-MET has been described in solid tumors as well as in acute myeloid leukemia (AML), myeloma, and MPN." (PMID 26543328, 2015).